STAT1 (signal transducer and activator of transcription 1)
Diseases named in the same sentence as STAT1 in open-access papers (continued):
Sharing a sentence is not in itself a finding about the gene and the disease.
nephritis (5 papers, 2008 to 2024). Inflammation of renal tissue. "Genetically engineered mice expressing the phospho-deficient threonine 748-to-alanine (T748A) mutant STAT1 exhibited similar survival rates, high titers of anti-dsDNA IgG, and nephritis compared to their wild-type littermates." (PMID 39329714, 2024). "The overactive expression of STAT1 and STAT3, as well as the activated JAK–STAT signalling transduction, has been implicated in the progression of nephritis and the onset of proteinuria." (PMID 39245800, 2024). "STAT1 gene silencing (STAT1−/−) in this mouse model is accompanied by a decrease of CD4+ producing IFN-γ T cells, a milder course of nephritis and a remarkable decrease of auto-ab levels." (PMID 31849996, 2019).
oral candidiasis (5 papers, 2016 to 2024). Infection of the mucosal lining of the mouth with the fungus Candida albicans. "Two girls with primary immunodeficiency affecting IFN-γ and IL-17 production, and with mutations in their IL12RB1 and STAT1 genes, were treated for oral candidiasis with IVIG mouthwash." (PMID 36713426, 2022). "In conclusion, in this study, we show that the treatment of oral candidiasis with polyvalent human IgG mouthwash helped eliminate the infection in two patients with an IL-12Rβ1 deficiency and a STAT1 GOF mutation." (PMID 30627128, 2018). "In the cohort of patients with heterozygous STAT1 mutations, we observed episodes of oral candidiasis in 73 % (19/26) of patients, with a tendency to become chronic if untreated in 42 % (8/19) of these patients." (PMID 26604104, 2016).
pancreatic ductal adenocarcinoma (5 papers, 2024 to 2025). An infiltrating adenocarcinoma that arises from the epithelial cells of the pancreas. "In pancreatic ductal adenocarcinoma, tumor-associated macrophage–derived TGF-β1 induces PKM2 nuclear translocation, which activates STAT1 signaling and modulates immune checkpoint pathways." (PMID 40842995, 2025). "In pancreatic ductal adenocarcinoma, TGF-β1 derived from tumor-associated macrophages induces PKM2 nuclear translocation and enhances STAT1-mediated PD-L1 transcription, linking glucose metabolism to immune escape." (PMID 40842995, 2025).
preeclampsia (5 papers, 2014 to 2023). Preeclampsia is a hypertensive disorder of pregnancy that is characterized by new-onset hypertension with proteinuria presenting after 20 weeks of gestation, and depending on mild or severe forms may initially present with severe headache, visual disturbances, and hyperreflexia. "Clinical data have revealed that nuclear factor of activated T cells-1 (NFAT-1), STAT1, and activator protein-1 (AP-1) were over-activated in monocytes of early-onset preeclampsia." (PMID 38235138, 2023). "Conversely, NFAT-1, STAT-1, and AP-1 are down-regulated in T cells of early-onset preeclampsia." (PMID 38235138, 2023). "A1AT exhibited an antioxidant role in preeclampsia by reducing ROS and MMP9 and increasing SOD through inactivation of STAT1/p38 signaling." (PMID 32231131, 2020). "It has been demonstrated than A1AT reduces p38 MAPK activity, as well as STAT1, H2O2, ROS generation and inflammatory cytokines in preeclampsia models." (PMID 32231131, 2020).
pulmonary hypertension (5 papers, 2015 to 2025). Increased pressure within the pulmonary circulation due to lung or heart disorder. "Basic research has confirmed the involvement of STAT1 and STAT3 in the pathogenesis of pulmonary arterial hypertension, with STAT1 activation being closely associated with a pro-inflammatory phenotype, whereas STAT3 promotes cell survival and inhibits apoptosis." (PMID 40332339, 2025). "In IL6- and PH-Fib- (pulmonary hypertension adventitial fibroblast) stimulated macrophages, the blocking of STAT3 signalling gave rise to increased expression of STAT3-regulated genes associated with increased and prolonged STAT1 phosphorylation." (PMID 26512722, 2015).
vasculitis (5 papers, 2017 to 2025). "We also observed that LV transduction led to reduction of IFN-γ and phosphorylated STAT1 expression in patient-derived macrophages; and ameliorated macrophage mediated endothelial activation, considered to be the main driver of vasculitis in DADA2." (PMID 35529868, 2022). "Hartmann and colleagues evaluated the presence of STAT-1 transcripts in an experimentally induced vasculitis of human temporal arteries grafted in immunodeficient mice and found STAT-1 abundantly expressed in arteritic tissue lesions." (PMID 30886946, 2017). "For example, abatacept in CTLA4 haploinsufficiency, LRBA and DEF6 deficiencies; tocilizumab in STAT3 GOF; JAK inhibitors in STAT3 and STAT1 GOF patients; alemtuzumab for CD25 deficiency; PIK3δ inhibitors for APDS or anti-TNFα therapy for vasculitis in ADA2 deficiency." (PMID 34447369, 2021). "Genetic testing identified a pathogenic STAT1 gain-of-function variant NM_007315.3:c.812A>C p.(Gln271Pro), which resulted in a change of diagnosis to 31C immunodeficiency (OMIM:614162), discontinuation of subcutaneous immunoglobulins, and subsequent vasculitis treatment with JAK-inhibitor." (PMID 40226629, 2025).
abortion (4 papers, 2020 to 2025). the ending of pregnancy by removing a fetus or embryo before it can survive outside the uterus. "Furthermore, we showed that IL-27 regulated the expression of Tim-3 and Blimp-1 through the STAT1 signaling pathway and that transfer of TregsBlimp-1+ into an abortion-prone mouse model effectively reduced embryo absorption rate." (PMID 39171524, 2024). "Therefore, we speculated that the decrease in miR-410-5p may participate in spontaneous abortion by inhibiting the STAT1 signaling pathway to promote M1 polarization." (PMID 38178171, 2024).
adenoma (4 papers, 2013 to 2022). A neoplasm arising from the epithelium. "Dll1 demonstrated elevated expression in both residual and untreated adenoma tumors, similar to Stat1 expression." (PMID 23520493, 2013). "Furthermore, a recent study has shown that mice with specific deletion of STAT1 in intestinal epithelial cells (STAT1-DIEC) are more susceptible to AOM-DSS-induced CRC, exhibiting higher grade adenomas than their similarly treated littermate controls." (PMID 30538296, 2019). "Moreover, Stat1-Ido1 expression correlated with Lysozyme expression in human TCGA data and IDO1+ Paneth cells were present in adenomas of FAP patients, indicating that human CRC also contain neoplastic IDO1+ Paneth cells." (PMID 32444775, 2020).
AIDS (4 papers, 2018 to 2025). A syndrome resulting from the acquired deficiency of cellular immunity caused by the human immunodeficiency virus (HIV). "In addition, three SNPs (IL1B rs1143623, STAT1 rs1467199 and STAT1 rs2066804) were associated with CD4+ T cell counts in patients with AIDS." (PMID 40331958, 2025).
anemia (4 papers, 2011 to 2022). A reduction in the number of red blood cells, the amount of hemoglobin, and/or the volume of packed red blood cells. "We describe a rare case of STAT1 mutation with recurrent CMC, lung infections, and anemia." (PMID 36105803, 2022). "However, this faster response did not lead to accelerated recovery from anemia in ISG15-/- mice (data not shown), a phenotype reminiscent to that described in STAT1-deficient mice." (PMID 22022510, 2011).
aneurysm (4 papers, 2022 to 2024). Bulging or ballooning in an area of an artery secondary to arterial wall weakening. "ARNTL2 and STAT1 are involved in hyperglycemic metabolism and coagulation-related regulation of T2DM, causing aneurysms." (PMID 36561297, 2022). "Taken together, neutrophils’ role in aneurysm development in STAT1 GOF CMC should be explored further as it may help elucidate immune mechanisms contributing to aneurysm formation in general." (PMID 37358695, 2023). "Moreover, as the downstream targets of JAK2, phosphorylation of signal transducer and activator of transcription 3 and 1 (p-STAT1 and p-STAT3) were also significantly higher in fusiform aneurysms compared with the normal cerebral arteries." (PMID 38741091, 2024). "We further determined whether Axl promotes macrophage polarization toward the M1 phenotype by activating STAT1/HIF-1α signaling, which promotes aneurysm rupture." (PMID 37223093, 2023).
antibody deficiency (4 papers, 2018 to 2025). "While functional antibody deficiency is known to associate with STAT1 gain-of-function, impairment of humoral immune response in phagocytic disorders is not well delineated." (PMID 36203563, 2022).
aplastic anemia (4 papers, 2022 to 2026). Anemia resulting from bone marrow failure (aplastic or hypoplastic bone marrow). "Nonetheless, to our knowledge, the present research represents the first report of the p.Cys174Arg STAT1 GOF variant in a patient with an inborn error of immunity developing aplastic anemia." (PMID 36826612, 2023). "Next, the most remarkable features associated with STAT1 signaling dysregulation were examined: in both pure red cell aplasia and aplastic anemia, CD8+ T cell genetic variants and mutations display enhanced signaling activities related to the JAK-STAT pathway." (PMID 36826612, 2023). "Since STAT1 GOF is associated with aplastic anemia, our patient's p.Cys174Arg variant was deemed causal for her aplastic anemia as well." (PMID 36826612, 2023). "Thus, the STAT1 signaling dysregulation has remarkable features: in PRCA and aplastic anemia, CD8+ T cell genetic variants and mutations are enriched for signaling related to the JAK-STAT pathway." (PMID 36826612, 2023). "Four out of 6 idiopathic aplastic anemia cases, compared to 6 cases of non-aplastic anemia, displayed increased STAT1 activity, showing p-STAT1 staining of BM core sections (gastric sections have been used as positive controls according to monoclonal antibody manufacturer’s indications)." (PMID 36826612, 2023). "Despite rare, aplastic anemia is more common than STAT1 GOF." (PMID 36826612, 2023). "In light of these findings, it is worthwhile to consider whether JAK inhibitor therapy may be beneficial for aplastic anemia patients with STAT1 hyperactivation." (PMID 36826612, 2023). "Interestingly, in a cohort of six patients with idiopathic aplastic anemia, enhanced phospho-STAT1 levels were observed on BM immunostaining." (PMID 36826612, 2023). "Interestingly, IFNγ and TNF-α have been described as possibly implicated in the pathophysiology of aplastic anemia and abnormal STAT1 activation was demonstrated in BM samples of few aplastic anemia patients." (PMID 35898506, 2022). "This prompted us to wonder whether aplastic anemia without a congenital STAT1 GOF variant might also have a similar pattern of STAT1 hyperactivation." (PMID 36826612, 2023). "However, the possibility that aplastic anemia developed coincidentally with the patient's STAT1 GOF mutation cannot be ruled out." (PMID 36826612, 2023). "Although STAT1 GOF is rare, aplastic anemia is a more common condition; therefore, we explored STAT1 functional role in the pathobiology of BM failure." (PMID 36826612, 2023). "In more details, p-STAT1 expression was examined by IHC on BM sections from 6 cases of idiopathic aplastic anemia and 6 of non-aplastic benign anemia." (PMID 36826612, 2023).
autoimmune lymphoproliferative syndrome (4 papers, 2021 to 2024). Autoimmune lymphoproliferative syndrome (ALPS) is a rare, inherited disorder characterized by non-malignant lymphoproliferation, multilineage cytopenias, and a lifelong increased risk of Hodgkin's and non-Hodgkin's lymphoma. "For certain IEIs, including hyper-IgE syndrome, STAT1-gain of function, autoimmune lymphoproliferative syndrome, and activated PI3K delta syndrome, FCM offered suggestive evidence, necessitating subsequent genetic testing for confirmation." (PMID 39072316, 2024).
celiac disease (4 papers, 2017 to 2025). An autoimmune genetic disorder with an unknown pattern of inheritance that primarily affects the digestive tract. "IRF1 plays a role in triggering gluten intolerance that itself is being suppressed by STAT1." (PMID 29379596, 2017). "The most significantly up-regulated genes in celiac disease were TAP1, HLA-E, HCP5, STAT1, GBP1, STAT1, LOC100419583, and GBP4 and the down-regulated ones were IDS, PKIB, FBXO2, OXT, and ADI1." (PMID 36011206, 2022).
cervical squamous cell carcinoma (4 papers, 2022 to 2024). A squamous cell carcinoma arising from the cervical epithelium. "It has been reported that Jak-STAT signaling pathway can contribute to resistance of cervical squamous cell carcinoma by mediating key activator protein as STAT1/STAT2." (PMID 35392800, 2022). "BRCA1 enhanced the sensitivity of cervical squamous cell carcinoma (CSCC) patients to cisplatin-based CCRT by up-regulating STAT1 to activate the JAK/STAT pathway." (PMID 35409328, 2022). "In patients with squamous cervical cancer, APOA1 overexpression can reduce the sensitivity of cervical squamous cells to carboplatin by regulating the expression of STAT1, CD81, C3, and TOP2A." (PMID 38212711, 2024).
chronic lymphocytic leukemia (4 papers, 2013 to 2024). "However, in chronic lymphocytic leukemia patients, the effects of fludarabine on STAT1 were transient, leading to increased STAT1 expression and therapeutic resistance." (PMID 39518046, 2024). "Another group demonstrated that TLR9 signaling by CpG-B ODNs leads to NF-kB-dependent production of autocrine IL-10, which then activates JAK/STAT pathway-dependent tyrosine phosphorylation of STAT1 proteins and thereby engenders an apoptotic pathway in human chronic lymphocytic leukemia B-cells." (PMID 23561041, 2013).
chronic myeloid leukemia (4 papers, 2022). "The dependence of BCL6 expression on STAT1 has been observed in imatinib-treated chronic myeloid leukemia cells." (PMID 36377663, 2022). "Fludarabine, a chemotherapeutic agent for chronic myeloid leukemia, promotes viral replication by targeting signal transducers and activator of transcription 1 (STAT1)." (PMID 35719333, 2022).
chronic obstructive pulmonary disease (4 papers, 2012 to 2022). A chronic and progressive lung disorder characterized by the loss of elasticity of the bronchial tree and the air sacs, destruction of the air sacs wall, thickening of the bronchial wall, and mucous accumulation in the bronchial tree. "Downregulation of STAT1 has been shown to inhibit inflammation in respiratory diseases, e.g., chronic obstructive pulmonary disease, and potentially to treat severe COVID-19 disease." (PMID 35280986, 2022). "In ASMC from people with chronic obstructive pulmonary disease (COPD), TNF-α induced CXCL10 via NF-κB activation, whereas IFNγ only induced a weak activation of NF-κB and activated STAT-1 as well, but not AP-1." (PMID 23034049, 2012).
cognitive decline (4 papers, 2015 to 2024). "Our results suggest that the role of CRY2 in cognitive decline may be due to its interaction with CISH, which subsequently inhibits p-STAT1 expression." (PMID 39012854, 2024).
common variable immunodeficiency (4 papers, 2021 to 2025). "A group of six patients with Common Variable Immunodeficiency (CVID) who had no pathogenic mutations identified in currently known IEI genes by NGS and no rare VUS in STAT1 were used as disease controls." (PMID 36722341, 2023). "Interestingly, inhibited Treg cell development and altered STAT1-mediated gene transcription were detected in a STAT1 GOF patient with common variable immunodeficiency (CVID) symptoms - but without classical IPEX-like symptoms." (PMID 37140667, 2023).
enteritis (4 papers, 2022 to 2025). Inflammation of the small intestine. "In CASP8-deficient mice, STAT1 activation in epithelium aggravated the sensibility toward bacterial-induced enteritis, intestinal inflammation, and lethality." (PMID 35795789, 2022). "Western Blot analysis confirmed an increased STAT1 phosphorylation at Tyr701 during Salmonella induced enteritis compared to tissue derived from C. rodentium infection and steady state conditions." (PMID 34497340, 2022). "Here, we demonstrate that epithelial STAT1 signaling is essential for host defense during bacterial enteritis by controlling cell extrusion in the intestinal epithelium." (PMID 34497340, 2022). "To study the role of STAT1 upstream of Caspase-8 during gastrointestinal infection we subjected control, Casp8ΔIEC mice and Casp8ΔIECxStat1−/− mice to the streptomycin mouse model for Salmonella Typhimurium induced enteritis." (PMID 34497340, 2022).
enteropathy (4 papers, 2017 to 2021). "STAT1 and STAT3: enteropathy, severe viral and bacterial infections, and endocrinopathy." (PMID 34122435, 2021).
enthesitis (4 papers, 2019 to 2024). Inflammation at the site of insertion of ligaments, tendons, and other fibrous structures into bone. "In parallel, the inhibition of the JAK/STAT1 pathway resulted in clinical and histological improvement of enthesitis." (PMID 35892597, 2022). "In mice with a low expression of A20 (a modulator of signal transducer and activator of transcription 1/STAT1/-dependent gene transcription) in myeloid cells, early enthesitis has been found." (PMID 35892597, 2022). "In vivo inhibition of the Jak-STAT1 pathways resulted in a significant reduction of enthesitis, both clinically and histopathologically." (PMID 31722720, 2019). "Pre-clinical studies suggest a fundamental role for JAK signalling in the pathogenesis of enthesitis, and upadacitinib has been shown to inhibit the phosphorylation of the signalling molecule STAT1 in entheseal cells, leading to reduced production of the inflammatory cytokines TNF and IL-17." (PMID 38331400, 2024).
eosinophilic esophagitis (4 papers, 2022 to 2025). Eosinophilic esophagitis (EoE) is a chronic, allergic disease of the esophagus characterized clinically by symptoms of esophageal dysfunction (including vomiting, dysphagia, feeding disorders, food impaction and abdominal pain) which persist after treatment with proton pump inhibitors (PPIs). "A case report of treatment refractory eosinophilic esophagitis associated with a STAT1 GOF alteration was recently published." (PMID 36050429, 2023). "Modern genomic technologies have revolutionized eosinophilia evaluation, with whole exome sequencing (WES) uncovering pathogenic STAT6 mutations in pediatric allergic cases and next-generation sequencing (NGS) identifying disease-associated STAT1 variants in familial eosinophilic esophagitis (EoE)." (PMID 41141324, 2025).